EYA1 (EYA transcriptional coactivator and phosphatase 1)
Description:
Functions both as protein phosphatase and as transcriptional coactivator for SIX1, and probably also for SIX2, SIX4 and SIX5 (By similarity). Tyrosine phosphatase that dephosphorylates 'Tyr-142' of histone H2AX (H2AXY142ph) and promotes efficient DNA repair via the recruitment of DNA repair complexes containing MDC1. 'Tyr-142' phosphorylation of histone H2AX plays a central role in DNA repair and acts as a mark that distinguishes between apoptotic and repair responses to genotoxic stress. Its function as histone phosphatase may contribute to its function in transcription regulation during organogenesis (By similarity). Also has phosphatase activity with proteins phosphorylated on Ser and Thr residues (in vitro) (By similarity). Required for normal embryonic development of the craniofacial and trunk skeleton, kidneys and ears (By similarity). Together with SIX1, it plays an important role in hypaxial muscle development; in this it is functionally redundant with EYA2 (By similarity).
Synonyms: BOP; BOR; BOS1; OFC1; OTFCS
Tractability: PROTAC: UniProt records ubiquitination sites on it; ubiquitination databases record sites on it.
Safety:
Unwanted effects reported when the protein is acted on. In parentheses: how it was acted on, where the effect was seen, and who reports it.
peptic ulcers (source: ClinPGx)
Gene: Protein-coding gene on chromosome 8 (71,197,432 to 71,592,025, reverse strand). Ensembl gene ENSG00000104313.
Subcellular location: Cytoplasm; Nucleus
Subcellular location (Human Protein Atlas): Nuclear bodies; Nucleoplasm; Primary cilium; Vesicles
Pathways (Reactome):
DNA Repair: Recruitment and ATM-mediated phosphorylation of repair and signaling proteins at DNA double strand breaks
Developmental Biology: Formation of the ureteric bud
Gene Ontology:
Molecular function: histone H2AXY142 phosphatase activity; protein binding; protein serine/threonine phosphatase activity; protein tyrosine phosphatase activity
Biological process: double-strand break repair; positive regulation of DNA repair; response to ionizing radiation; anatomical structure morphogenesis; cell differentiation; negative regulation of extrinsic apoptotic signaling pathway in absence of ligand; protein sumoylation; sensory perception of sound; chromatin remodeling
Cellular component: cytoplasm; nuclear body; nucleoplasm; nucleus
Genetic constraint (gnomAD): Loss-of-function variants: 11 observed, 62.54 expected, observed/expected ratio (o/e) 0.18, 90% interval 0.11 to 0.29. The upper end of that interval is the gene's LOEUF score, 0.29, which puts it in group 1 of 6, group 1 being the genes least tolerant of losing a copy. Missense variants: 540 observed, 636.65 expected, observed/expected ratio (o/e) 0.85, 90% interval 0.79 to 0.91. Synonymous variants: 227 observed, 235.22 expected, observed/expected ratio (o/e) 0.97, 90% interval 0.87 to 1.08.
Gene-disease validity (ClinGen):
ClinGen rates the evidence that EYA1 causes each of these diseases.
branchio-oto-renal syndrome (autosomal dominant): Definitive.
Homologues: Orthologues: chimpanzee EYA1 (99% identical), macaque EYA1 (99% identical), guinea pig EYA1 (98% identical), dog EYA1 (98% identical), mouse Eya1 (96% identical), pig EYA1 (96% identical), rabbit EYA1 (94% identical), rat Eya1 (94% identical), zebrafish eya1 (88% identical), tropical clawed frog eya1 (87% identical), Drosophila melanogaster eya (46% identical), Caenorhabditis elegans eya-1 (22% identical). Paralogues in human: EYA4 (73% identical), EYA2 (59% identical), EYA3 (50% identical).
Diseases named in the same sentence as EYA1 in open-access papers:
EYA1 is named in the same sentence as 98 diseases in open-access papers, as found by Europe PMC text mining. Sharing a sentence is not in itself a finding about the gene and the disease. The quoted sentences say what the papers report.
BOR syndrome (31 papers, 2007 to 2025). "A distinct cochlear hypoplasia phenotype—characterized by a preserved first half of the basal turn and hypoplastic, anteriorly displaced upper turns—has been described in BOR syndrome and linked to EYA1 variants." (PMID 40515822, 2025). "In this study, we define the molecular basis of BOR syndrome in a family segregating a previously reported heterozygous canonical splice site variant in EYA1." (PMID 38213489, 2024). "In humans, mutations in SIX1/SIX2 and EYA1 are likely to affect downstream events, which contribute to various phenotypes of BOR syndrome." (PMID 38353121, 2024). "Genetic evaluation revealed a previously reported heterozygous canonical splice site variant in EYA1, variants in which are known to account for most instances of BOR syndrome." (PMID 38213489, 2024). "Approximately 40% of patients with BOR syndrome carry a pathogenic mutation in EYA1, whereas 9-10% have mutations in SIX1 or SIX5." (PMID 38353121, 2024). "We also reported a novel pathogenic variant of EYA1, and infrequent pathological data of renal biopsy in BOR syndrome." (PMID 37612603, 2023). "In the present study, we detected EYA1 P/LP variants in 25% of patients with atypical BOR syndrome and in 86% of typical patients." (PMID 35046468, 2022). "In summary, we report the detection rate of EYA1 P/LP variants in patients with typical and atypical BOR syndrome." (PMID 35046468, 2022). "A heterozygous c.1082G>A (p.Arg361Gln) variant of EYA1, a gene responsible for Branchiootorenal syndrome 1 (BOR1), was identified in family 1636." (PMID 35248088, 2022). "With the development of genetics in recent years, the causative genes of BOR syndrome in several patients have been recognized, such as EYA1 which is most commonly associated causative gene." (PMID 36333735, 2022). "Eya1 homozygous-deficient mice lack ears and kidneys, and Eya1 heterozygous-deficient mice present with phenotypes resembling BOR syndrome." (PMID 33880118, 2021). "BOR syndrome is inherited in an autosomal dominant pattern, with a prevalence of 1/40,000 in Western countries and results from a mutation in the EYA1 gene." (PMID 34449578, 2021). "Some syndromic CAKUT encompass characteristic extrarenal manifestations, such as hearing loss and neck anomalies in BOR syndrome (EYA1), optic nerve coloboma in renal coloboma syndrome (PAX2), and hyperuricemia and diabetes in RCAD syndrome (HNF1B)." (PMID 32164334, 2020). "Meanwhile, EYA1 mutations account for 30%–35% of BOR syndrome, which is characterized by branchial defects, malformations of the outer, middle, and inner ear associated with deafness, and renal anomalies." (PMID 32164334, 2020). "Mutations in PAX2 and EYA1 cause the autosomal dominant disorders renal coloboma syndrome and BOR syndrome, respectively." (PMID 32164334, 2020). "EYA1 variants can be detected in approximately 40% of persons with BOR syndrome and approximately 20% of those patients carried complex genomic rearrangements of EYA1." (PMID 30548429, 2019). "Although previous studies have reported many BOR-related mutations, this is the first time that BOR syndrome has been investigated genetically and pathogenic mutations in EYA1 have been detected in a Chinese family with BOR syndrome." (PMID 30086703, 2018). "Since the role of EYA1 in development is crucial, it is related to four diseases as a pathogenic gene: otofaciocervical syndrome, anterior segment anomaly, BO syndrome, and BOR syndrome." (PMID 30086703, 2018). "In fact, the only instance of a positive genetic diagnosis associated with unilateral hearing loss was in a patient with a family history of BOR syndrome caused by a truncating variant in EYA1, a well-recognized phenotype–genotype association." (PMID 26969326, 2016). "Mutations in SIX1 gene (MIM 601295), the human homolog of sine oculis, encoding a DNA binding protein that interacts with EYA1, have also been associated with BOR syndrome although less frequently than EYA1 mutations." (PMID 23506628, 2013).
BOR syndrome (continued). "In the Korean population, there have been only 3 case reports of patients with BOR/BO syndrome carrying EYA1 mutations, and this study adds to the genotypic and phenotypic spectrum of BOR syndrome in the East Asian population." (PMID 23840632, 2013). "Mice carrying a hypomorphic Eya1 mutation have inner ear and other malformations that are reminiscent of those found in patients with BOR syndrome." (PMID 19389353, 2009). "BOR syndrome caused by EYA1, SIX1 and SIX5 mutations leads to kidney and urinary tract malformations and hearing impairment." (PMID 19389353, 2009). "EYA1 mutations are detected in approximately 40% of patients with clinical diagnosis of BOR syndrome." (PMID 17216254, 2007). "This study highlights the phenotypic heterogeneity within the same family, reports the occurrence of renal failure and adverse pregnancy outcomes in a female patient at reproductive age with BOR syndrome, and enriches the mutational spectrum of pathogenic variants in the EYA1 gene." (PMID 38627775, 2024). "In EYA1-related BOR syndrome, EYA1 variants affect EYA-SIX network and lead to abnormalities of nephron progenitors, which may result in congenital anomalies of the kidneys." (PMID 37612603, 2023). "It is worth noting that case 2 and his brother were patients with BOR syndrome but EYA1 variants were excluded in peripheral blood of their parents, in which the most probable mechanism is germinal mosaicism of EYA1 in one of their parents, just as Miyagawa’s report." (PMID 37612603, 2023). "Mutations in the human EYA1 gene have been reported associated with BOR syndrome." (PMID 36316881, 2022). "We found the variants responsible for the disease in one patient diagnosed with Waardenburg syndrome, presenting the variant responsible for the disease in MITF, and one patient diagnosed with BOR syndrome was found to present with the pathogenic variant in EYA1." (PMID 33297549, 2020). "In summary, we report a novel nonsense mutation in EYA1 as a causative mutation for BOR syndrome." (PMID 30086703, 2018). "Analysis of the molecular mechanisms, by which mutations in EYA1 lead to BOR syndrome, showed that several different aspects of Eya1 protein function can be affected, as for example the phosphatase activity, the interactions of Eya1 with Six, Dach, and Gα subunits, or both." (PMID 24489909, 2014). "Mutations of the EYA1 gene are found in approximately 40% of patients with BOR syndrome." (PMID 23840632, 2013). "The novel EYA1 mutations may add to the genotypic and phenotypic spectrum of BOR syndrome in the East Asian population." (PMID 23840632, 2013). "Interestingly, SIX1, SIX5, and EYA1 are associated with BOR syndrome." (PMID 30086703, 2018). "The novel EYA1 mutations identified in this study adds to the genotypic and phenotypic spectrum of BOR syndrome in the East Asian population and the clinical results of this study may provide evidence for recommending proper means of auditory rehabilitation in patients with BOR/BO syndrome." (PMID 23840632, 2013). "Two cases each carried disease-causing variants in SALL1 and EYA1, both well-known autosomal dominant syndromic monogenic CAKUT genes (Townes-Brocks syndrome 1, MIM #107480; and branchiootorenal syndrome 1, MIM #113650)." (PMID 36922632, 2023). "The results showed that one suspected pathogenic mutation was located on chromosome 8; chr8: 72184133, detected in EYA1 gene, which was partially related to the phenotype of the BOR syndrome." (PMID 36316881, 2022). "The presence of branchial cysts, cervical fistulae, external ear anomalies and mild renal pyelectasis suggested the clinical diagnosis of BOR syndrome and the analyses of EYA1, SIX1, and SIX5 genes were performed by next generation sequencing (NGS)." (PMID 36183088, 2022). "Genetic analysis revealed a microdeletion at chromosome 8q13.2-q13.3 encompassing EYA1 gene, this patient was finally diagnosed with BOR syndrome." (PMID 36333735, 2022).
BOR syndrome (continued). "Mouse models of BOR syndrome, Eya1+/− and Six1+/− heterozygous mice, exhibit postnatal middle ear defects and pathology, which likely contribute to the deafness phenotypes." (PMID 36299576, 2022). "40% of BOR syndrome cases are due to Eya1 haploinsufficiency, with mouse models affecting Eya1, mimicking many of the defects found in patients." (PMID 36299576, 2022). "The phenotype of Eya1-heterozygous mice resembles the symptoms of human patients suffering from BOR syndrome." (PMID 24489909, 2014). "To date, EYA1 transcript analysis have been reported only for five other patients with BOR syndrome, two of which presented unstable EYA1 transcripts and three aberrant transcripts." (PMID 23506628, 2013). "In humans, mutations in EYA1 and its interacting partners SIX1 and SIX5 have been identified as causing BOR syndrome." (PMID 19389353, 2009). "Deletion of the Six1 or Eya1 genes in mice has confirmed the important role of these genes during the development of inner ear and other organs affected in BOR syndrome." (PMID 19389353, 2009). "While CD is not strictly classified as a genetic kidney cystic disease, it has been associated with mutations including EYA1 and SIX1, which are linked to conditions like BOR syndrome, or other causes of congenital anomalies of the kidney and urinary tract (CAKUT)." (PMID 38254980, 2024). "The features may overlap with branchiootorenal syndrome since the EYA1 and SALL1 genes are involved in the same biochemical pathways." (PMID 37468646, 2024). "Genetic analysis reveals that mutations in EYA1, SIX1 and SIX5 cause BOR syndrome, an autosomal dominant developmental defect characterised by branchial and external ear malformations, hearing loss and renal anomalies." (PMID 38353121, 2024). "There are some reports of patients with atypical BOR syndrome, which does not satisfy the clinical criteria for typical BOR syndrome, despite carrying EYA1 or SIX1 mutations." (PMID 35046468, 2022). "In 1997, the human homolog of the Drosophila eyes absent gene (EYA1 MIM#601653) was reported as the first causative gene for BOR syndrome." (PMID 30548429, 2019). "EYA1, the human homolog of the Drosophila “eye absent” gene on chromosome 8q13.3, is recognized as one of the most important genes associated with BOR syndrome." (PMID 30086703, 2018). "In 1997, scientists studied seven patients with BOR syndrome and identified a novel causative gene, known as EYA1 (eyes absent)." (PMID 30086703, 2018). "No specific hot spot has been demonstrated for EYA1 mutations causing BOR syndrome and most of the mutations are unique to individual families." (PMID 23840632, 2013). "Mutations in EYA1, SIX1 and SIX5 genes have been associated with BOR syndrome." (PMID 23840632, 2013). "Here, we report the clinical and genetic diagnosis of an Italian patient with BOR syndrome associated with focal segmental glomerulosclerosis and a novel EYA1 splice site mutation." (PMID 23506628, 2013). "It is noteworthy that three cases from two unrelated families with EYA1 variants presented visual symptoms (progressive disturbance of vision, amblyopia and hypermetropia), but visual symptoms are not typically associated with BOR syndrome." (PMID 31427586, 2019). "In this study, we demonstrate pathogenicity of EYA1 c.1698+1G>A, propose a mechanism for dysfunction of mutant EYA1, and conjecture CYP51A1 as a potential genetic modifier of renal involvement in BOR syndrome." (PMID 38213489, 2024). "In contrast, the mutant G393S, which is derived from a patient with combined BOR syndrome and ocular defects did not affect any of the Eya1 protein characteristics addressed in this work and in previous studies." (PMID 24489909, 2014). "Mutations on the human ortholog of the Drosophila eyes absent gene (EYA1, OMIM 601653) are considered to be a major cause of BOR syndrome." (PMID 25135225, 2014). "Subject III-2 who is not affected by BOR syndrome harbored wild-type EYA1." (PMID 38213489, 2024).
breast cancer (14 papers, 2013 to 2025). A primary or metastatic malignant neoplasm involving the breast. "In breast cancer cells, miR-101 promotes apoptosis and inhibits cell proliferation, which is associated with increased expression of EYA1." (PMID 28947955, 2017). "In embryonic kidney or breast cancer cells, EYA1 dephosphorylates T58 on c-Myc using its threonine phosphatase activity, thereby preventing its ubiquitination." (PMID 39897043, 2025). "miRNA-101 was found to target different pathways that promote breast cancer cell apoptosis by inhibiting the expression of Jak2, EYA1 and SOX2 acting as a potential therapeutic target in breast cancer." (PMID 34200314, 2021). "Given the similarity of our results and those conducted by Cook et. al, we propose a mechanism of action of EYA1 in the pathogenesis of melanoma resembling its role in the pathogenesis of breast cancer." (PMID 29285235, 2017). "Among these, 11 CNVRs overlapped with 12 genes (GSTM2, RAB40B, HLA_DRB5, HLA_DRB6, EYA1, DOCK3, ANKS1B, CACNA1C, RAB11FIP3, BAGE, SGCZ, POM121c) and were specifically associated with breast cancer risk and OS." (PMID 29116104, 2017). "Since EYA1 was reported to increase cyclin D1 production and decrease phosphorylated γH2AX in breast cancer cells, we examined if these were the case in melanoma cells." (PMID 29285235, 2017). "In contrast, EYA1 induces cyclin D1 through its phosphatase activity in breast cancer, and SIX1 directly enhances the transcription of cyclin D1 in rhabdomyosarcoma tumor cells." (PMID 27203207, 2016). "In breast cancer EYA1 levels are increased, which promotes proliferation by activating cyclin D1." (PMID 29285235, 2017). "Meanwhile, combination regimens with specific pathway blockers (PI3K: LY294002; Akt: Perifosine; Wnt: XAV939) may be effective treatments for EYA1-dependent breast cancer." (PMID 27203207, 2016). "Similarly, over-expression of EYA1 in the breast cancer cell line BT-474 shows an effect on longer-term cell proliferation (>3 days) while having little effect at 24 hours post-seeding." (PMID 24367676, 2013). "Likewise, the tumorigenic role of EYA1 in breast cancer cells relies on its phosphatase function." (PMID 27203207, 2016). "Remarkable relation among EYA1, EYA2 and EYA3 genes with the LumB subtype are in accordance with the previous finding that EYA genes play an important role in breast cancer growth and metastasis as well as directing cells to the repair pathway upon DNA damage." (PMID 34112093, 2021). "Specifically, Six1 and EYA1 upregulated cyclin D; In contrast, DACH1 acted as an antagonist of cyclin D1 in breast cancer." (PMID 25322986, 2014). "Besides MYC itself, we find upregulation of other breast cancer stem cell factors (SOX2, SOX18, THY1, EYA1, GLI2, SALL1, GLIS1, CXCR4), suggesting that MYC HME cells adopt a stem-like state." (PMID 31942031, 2020). "We performed bioinformatics analysis of the data from the miRDB, Targetscan, Pictar, and miRanda websets to explore the molecular mechanism of miR-27a as an oncogenic molecule in breast cancer, and found that six genes are overlapped, namely TMEM170B, GPAM, PPAP2B, ST6GALNAC3, EYA1, and PPARG." (PMID 29367600, 2018).